JUN (Jun proto-oncogene, AP-1 transcription factor subunit)
Diseases named in the same sentence as JUN in open-access papers (continued):
Sharing a sentence is not in itself a finding about the gene and the disease.
cancer (continued). "A key finding was that a single contaminant can impact different cancers via distinct targets; for example, PFOS appears to target JUN in BRCA but MAPK14 in PRAD." (PMID 41246859, 2025). "Mechanistic studies revealed FS targets key molecules (STAT3, EGFR, ESR1, PTGS2, NF-κB1, and JUN), modulating PI3K-Akt, MAPK and cancer-related pathways." (PMID 40649400, 2025). "Downregulated genes again were enriched for transcription factors, which included cancer‐related ones such as MYC, JUN and JUNB." (PMID 39508147, 2025). "Based on this analysis, the genes STAT3, MYC, CTNNB1, ESR1, JUN, and BRCA1 emerged as pivotal genes, indicating their significant impact on each cancer type in response to radiation exposure." (PMID 41186627, 2025). "A study highlighted the role of Silibinin, an important component of Silybum marianum, in activating cancer cell apoptosis and enhancing ROS levels by the stimulation of the JNK/c‐JUN pathway." (PMID 40377005, 2025). "Given that proliferative behavior is fundamental to the progression of malignant tumors, we used MTT and colony formation assays to demonstrate that upregulation of GPX3 and JUN significantly inhibits the proliferation of TC cells." (PMID 40092686, 2025). "Other important cancer-related molecules and pathways were inhibited upon GCV treatment, for example, HIF1A, MAP2K1/2, PI3K, JUN, and HDAC." (PMID 38927982, 2024). "In the development and progression of cancer, AKT1, JUN, IL6, SRC, EGFR and BCL2 plays a critical role." (PMID 39011503, 2024). "Several PDA-associated pathways (cell cycle, stress response, Rho GTPase signaling) and cancer driver hub genes (EGFR and JUN) exhibited a cancer-specific rhythmic pattern intricately linked to the circadian clock." (PMID 38716727, 2024). "Additional genes included JUN, transcription factor and apoptosis repressor with caspase recruitment domain (ARC) that are commonly induced in cancers." (PMID 38110554, 2024). "JUN (c-JUN) particularly piqued our interest because several studies proposed a cooperative behavior between YAP and AP-1 in cancer cells." (PMID 39210147, 2024). "Examination of expression data of 32 types of tumors in the Pan-Cancer Co-Expression Analysis for the RNA-RNA interactions revealed a 94% positive correlation between JUNI and JUN levels in all cancer types examined." (PMID 38565943, 2024). "Mechanistically, the combination of MRTX849 and dasatinib inhibited JUN-dependent expression of ABCC1 and CCND1 in multidrug-resistant cancer cells." (PMID 39661665, 2024). "THz demethylation downregulates FOS, JUN, and CXCL8 genes, which are involved in cancer and apoptosis pathways." (PMID 36967404, 2023). "To explore the correlation of the JUN expression with ICI response, we conducted Spearman correlation analysis, and the obtained results showed that the TMB of 11 types of cancers as well as the MSI of 8 types of cancers." (PMID 37986345, 2023). "At the same time, we analyzed the TISIDB database and found a significant positively correlation between JUN expression level and lymphocytes, immunomodulators (including MHC molecule) and chemokines at pan-cancer level, especially in LGG." (PMID 37986345, 2023). "JUN, CXCR4, and WNT5A were the top three interaction DEGs in pathways in cancer; H6PD, FH, and ACO2, which associate with glucose metabolism, were the top three interaction DEGS in metabolic processes." (PMID 37601754, 2023). "As expected, the expression levels of NCBP2, c-JUN, and p-ERK were significantly higher in PDAC tissues than those in para-carcinoma tissues." (PMID 38001714, 2023). "To further test our conclusion, we compared the expression level of NCBP2, c-JUN, and p-ERK between PDAC and para-carcinoma tissue by IHC staining on tissue microarray." (PMID 38001714, 2023).
cancer (continued). "Previous reports using normal epithelial tissues and carcinomas revealed that warm enzymatic dissociation (i.e., at 37 °C) invoked a distinct ‘Warm Dissociation Signature’ enriched in FOS, FOSB, and JUN." (PMID 37254069, 2023). "Finally, ranking cancer driver mutations by their correlation with glutamine reveals that KRAS and ERBB4 have the strongest negative correlation (indicating that mutation is associated with a reduction of glutamine), and PRCC, JUN and PIK3CA mutations rank highly with an accumulation of glutamine." (PMID 36321551, 2022). "Among the top enriched transcription factor motifs, we identified JUN, ETV5, and IRF3, that are well-known to be involved in cancer development." (PMID 35130920, 2022). "Most of the NRF2 pathway-related genes showed extensively negative relationships with RNAss; for example, the expressions of FOS, JUN, MAF, MAFK, and PRRT2 in various cancers were negatively related to RNAss." (PMID 35242279, 2022). "FBW7 is a well-known E3 ligase that degrades multiple proteins, including Myc, JUN, Nothc1 and EZH2, in cancer cells." (PMID 35081978, 2022). "To elucidate the signaling pathways involved in WNK3-mediated PD-L1 regulation, we investigated several key signaling pathways, including JNK/c-JUN, ERK, p38, AKT, NF-κB, and JAK/STAT, which regulate PD-L1 transcription in cancer cells." (PMID 36357569, 2022). "Another study showed that the hypoxia-inducing factors HIF2α, together with JUN, regulated GLIS1 transcription in various cancer cells." (PMID 35216340, 2022). "Our PPI network analysis identified four hub genes (SLC2A1, VEGFA, JUN, and PTGS2) enriched in the cancer-related pathways." (PMID 36482897, 2022). "In some cancers, co-expression of IEGs, such as FOS, JUN, and EGR1, was positively correlated with poor survival." (PMID 36505794, 2022). "We therefore set out to quantify to what extent the PD-L1 mRNA level (CD274) in cancer patients can be predicted by activity of the relevant TFs MYC, HIF1A/2A, JUN, IRF1, STAT1/3, NFKB, and NRF2." (PMID 35289334, 2022). "By activating transcriptional factors from the JUN and FOS family, intracellular bacteria can generate gene signatures that are consistent with cancer cell invasion, metastasis, DNA damage repair and cell dormancy." (PMID 36385528, 2022). "Accordingly, specific inhibition of JUN in fibroblasts successfully suppresses CAF functions, for example, VEGFC expression and secretion, and thereby curbs cancer development." (PMID 36438487, 2022). "Most genes related to signal transduction in the cytoplasm were inactivated in the pathway of the Molecular Mechanism of Cancer; however, the gene expression of NF-κB, c-FOS, c-JUN, MDM2, AURORA-A, BBC3, BIM, and p21CIP1 was significantly increased." (PMID 35328637, 2022). "USP28 levels are increased in cancer compared with in normal cells due to a feed‐forward loop, driven by increased amounts of oncogenic transcription factors such as c‐MYC and c‐JUN." (PMID 35364627, 2022). "Alternatively, in already transformed cancer cells and particularly in SCC cancer cells, USP28 acts as an oncoprotein facilitating cancer homeostasis and proliferation via stabilization of oncogenic substrates, such as c-MYC, c-JUN, NOTCH1, ∆Np63, and CCNE." (PMID 34685632, 2021). "To evaluate a potential role for genetic disruption of JUN in human LADC, we analyzed The Cancer Genome Atlas (TCGA) data from 230 LADC cases." (PMID 34236045, 2021). "Curcumin suppresses the other proliferation signaling pathways, such as PI3K, AKT, mTOR, AP1 (JUN and FOS), JNK, JAK/STAT, PKC, CMYC, MAPK, ELK, CDKs, iNOS, and Wnt/β-catenin, which confirmed its vital role in the prevention of cancer progression." (PMID 34485117, 2021). "In ESCC cell lines, we examined all AP-1 transcription factors including JUN, FOS, MAF, and ATF family members and found that FOSL1, MAFK, BATF, and ATF5 are upregulated compared to non-cancer cells." (PMID 34722266, 2021).
cancer (continued). "Different observations suggest that C-JUN, a member of the JUN sub-family, plays an important role in various types of cancers." (PMID 33946771, 2021). "CYT-low COAD tumors contained significantly more cancer genes harbored within chromothriptic regions (TCF12, NF1, ERBB2, JUN, JAK1 and BCL10)." (PMID 34316699, 2021). "YAP stimulates tumor cell proliferation by amplifying the expressions of oncogenes, such as MYC and AP-1 family members (JUN and FOS-like factors), thus affecting DNA duplication, DNA repair and mitosis in cancers." (PMID 33413409, 2021). "MYC, SOX2, JUN, or ARNT was significantly correlated with THBS2 in most cancers, including COAD and PAAD." (PMID 34804159, 2021). "On the other hand, oncogene and cancer related genes, such as MYC, FOS, JUN, and growth promoting genes were upregulated in U1 AMO, but downregulated in U1 OE." (PMID 31911652, 2020). "The expression levels of JUN, SFN, HSPB1, and CD47 in cancer cells and the expression levels of KLRB1, CD48, GZMK, and LY6E in CD8+ T cells were consistent with the scRNA-seq results." (PMID 33083004, 2020). "Members of the Jun family (JUN and JUND), that are key subunits of the transcription factor AP-1, are designated as MRs in healthy and cancer cells, given their crucial role in cell cycle progression, differentiation and programmed cell death." (PMID 32471360, 2020). "Protein–protein interaction analysis of common DEGs in L. brandtii showed that the most significant core genes were CXCL1, MMP9, JUN, ANXA2, and F5, which regulate immune response and cancer progression." (PMID 32256671, 2020). "MAPK signalling pathway (JUN, RAC1, MAPK8, MYC and FOS) and transcriptional misregulation in cancer (CDKN1A, MYC and FOXO1)." (PMID 32457348, 2020). "And indeed, the mRNA levels of JUN and the membrane-bound TNF of these human cancer cells were also upregulated in response to treatment with MTAs." (PMID 31645676, 2020). "We found significant joint over expression of the JUN and FOS proto oncogenes in a cluster of cells for sample ETV6.RUNX1.2, suggesting deregulation in stress/cancer genes." (PMID 32415257, 2020). "Crosstalk of gas signaling molecules with other signaling pathways such as JUN, JAK2, JAK3, and NF-κB, upregulates p38MAPK, hypoxia, immune cell, and cancer metastasis signaling." (PMID 30972102, 2019). "Several transcription factors, such as oncoprotein FoxM1 and c-JUN, have been reported to promote MELK in cancer cells." (PMID 29416794, 2018). "Enrichment of similar factors was found for cancer and aging, for example, EP300, FOS, and JUN, among others." (PMID 29504244, 2018). "Drugs of arsenic trioxide, vinblastine and LGD-1550, interacting with JUN, along with nadroparin that interacts with FOS, all have anti-cancer activities." (PMID 29321498, 2018). "The anticancer activity of tylophorine, an alkaloid from Tylophora indica was also demonstrated to be mediated by c-JUN in HONE-1, NUGC-3 and HepG2 carcinoma cells." (PMID 30042885, 2018). "Although the reprogramming mechanisms of somatic cells and cancer cells are distinct, our results elucidate the function of MBD3 and c-JUN in reprogramming." (PMID 27894081, 2017). "Some studies found that the JUN/FOS dimer, namely AP-1 complex, was involved in certain cancer genesis, and it can be the potential targeted therapeutic genes for certain cancer therapy." (PMID 28673327, 2017). "In the identified pan-cancer FFLs, CCND1 and JUN are drug targets of ATO, which span three pan-cancer FFLs." (PMID 26655252, 2016). "Second, we constructed the pan-cancer FFLs subnetworks that were targeted by the nine anticancer drugs, in which ATO has two drug targets, CCND1 and JUN." (PMID 26655252, 2016). "Pathway results showed that seed genes PTGS2, HDAC1, JUN, and SLC2A1 were enriched in pathway in cancer, seed genes HDAC1 and CDC20 were involved in cell cycle, and seed gene MTHFR participated in methane metabolism." (PMID 27034707, 2016).
cancer (continued). "Most of the genes, that are involved in many of the significantly enriched pathways, also play a role in pathways in cancer such as PTEN, JUN, AKT2, HSP90AA1, the latter of which was already described to influence radiosensitivity and chemosensitivity." (PMID 26328888, 2015). "Three of these genes, JUN, EGR1, and AKAP12, are involved in the control of cell proliferation and cancer progression." (PMID 24961511, 2014). "Several other phosphorylating substrates of PRKDC have also crucial role in cancer, like, c-Myc, PARP, c-JUN." (PMID 23437280, 2013). "• Exertion of anticancer effects through 3 major pathways: apoptosis (BIRC3, BIRC5, caspase-8, caspase-9, and PARP1), transcriptional dysregulation in cancer (CDKN1A, CDKN1B, MMP9, MYC, JUN, and RELA), and cancer progression (caspase-3, CCND1, CTNNB1, VEGFA, and Wnt-1)." (PMID 39181121, 2025). "Our data showed that inhibition of the JNK/c-Jun pathway in BRAFV600E CRC cell lines resulted in reduced cell proliferation and increased apoptosis, whereas its overexpression showed the opposite effect, unveiling a role of c- JUN in cancer cell survival." (PMID 40481178, 2025). "Among the DEGs positively modulated in SCE17-exposed cells, we can highlight genes involved in cancer progression, such as FOS, JUN, and JUNB proto-oncogenes, Cyclin Dependent Kinase Inhibitor 1A (CDKN1A), and Tumor Protein 53 Inducible Nuclear Protein 1 (TP53INP1)." (PMID 41440891, 2025). "In conclusion, JUN, NFKB1 and SP1 may jointly maintain the characteristics of cancer stem cells by regulating the stemness maintenance and telomerase activity of cancer stem cells, thus influencing the progression, treatment resistance and recurrence of BC." (PMID 40666524, 2025). "c-JUN is a member of the activated protein-1 (AP-1) TF family that is stimulated by upstream signals and can be transmitted by the JUN N-terminal kinase (JNK) to regulate gene expressions at the transcriptional level, thereby inducing cancer." (PMID 39376611, 2024). "JUN, part of the AP-1 transcription factor, is closely related to cell growth and differentiation, while PGF, a placental growth factor, plays roles in angiogenesis and cell proliferation in several cancers, including HCC." (PMID 39484208, 2024). "TCGA pan-cancer reverse-phase protein assay data showed that JUN mRNA level is positively correlated with mTORC1 activity in 27 of 32 cancer types (data not shown)." (PMID 37909334, 2023). "However, since the RIP-seq results were also validated with real-time RT-PCR, at least six genes related to “Pathways in cancer,” i.e., TGFB2, CREBBP, EP300, FOS, JUN, and MYC were certainly affected by the hnRNPM-AS1-S interaction." (PMID 37671887, 2023). "JUN and FOS are part of the transcription factor AP-1, which plays an important role in cell growth and the differentiation and overexpression of these two proteins leads to an increased expression of other oncogenes in several cancer entities." (PMID 37627150, 2023). "Therefore, the JUN and FOS gene families contribute significantly to cancer transformation and cell growth." (PMID 36967404, 2023). "This analysis validated the identification of genes that could be specific to cancer biology, such as IL7R, JUN, NR3C1 in Ba/Sq subtype, NPAS2, FOXQ1, GRHL3 in Luminal samples, or CDKN2C, FOXJ1, MEIS2, FGFR3 in both subtypes." (PMID 36944729, 2023).
cancer (continued). "In conclusion, the network pharmacology of this study was used to screen out the active compounds of SBG (baicalein and wogonin), 41 intersection targets (VEGFA, IL6, MAPK3, JUN, TNF, and other targets), and 20 main pathways (Pathways in cancer, IL-17, TNF signaling pathway and others)." (PMID 36415861, 2022). "Moreover, we illustrated downstream‐targeted genes of JUN, FOS, FOSB, EGR1, and ZFP36 and demonstrated that these targeted genes were involved in “positive regulation of cell death”, “pathways in cancer”, “PI3K‐Akt signaling pathway”, and so on." (PMID 35037412, 2022). "However, GSK3B (Glycogen Synthase Kinase 3 Beta) acts as a negative regulator in the phosphorylation of key cancer-related genes, such as APC, JUN, and CTNNB1/beta-catenin." (PMID 35645340, 2022). "In vitro cell experiments showed that downregulation of PBRM1 expression could significantly promote the cancer progression and epithelial‐to‐mesenchymal transition via the PBRM1‐c‐JUN‐VIM axis." (PMID 36178086, 2022). "Furthermore, data from different experimental models with reduced expression of JUN revealed that the involvement of JUN in HCC signaling pathways, which influenced cancer cell proliferation and migration." (PMID 36351994, 2022). "The three clusters generated contained genes or proteins involved in apoptosis (BIRC3, BIRC5, PARP1, CASP8, and CASP9), transcriptional dysregulation in cancer (CDKN1B, RELA, CDKN1A, MYC, JUN, and MMP9), and cancer progression (CCND1, CASP3, CTNNB1, WNT1, and VEGFA) pathways." (PMID 34836311, 2021). "Since transcription factor-mediated gene transcription depends on both its accessibility to cognate binding sites and its abundance, the authors determined gene expression of JUN and FOS family members and found overexpression of FOS, FOSB, and FOSL1 in the cancer." (PMID 34722266, 2021). "Meanwhile, c-JUN, HMOX1, and CTGF play an oncogenic role in cancer." (PMID 33579362, 2021). "Genes related to B and T cell maturation (e.g. CD37, CD79B, JCHAIN, IGLL1, VPREB3, CD52), ribosomal protein genes (RPS-*, RPL-*) and cancer/stress genes (e.g. PRAME, ARHGDIB, FOS, JUN) were within the most significantly deregulated genes between clusters in those samples." (PMID 32415257, 2020). "In addition, a list of known JUN-target genes, including MMP3, CD44, EGFR, ENPP246, and MGST147, were markedly upregulated in cancer cells with SH3RF3 overexpression." (PMID 32427938, 2020). "Other well-known cancer genes such as BRCA1, CHEK2, JUN, and MYC could also be found in the highly interconnected regions of the PPI network." (PMID 29540752, 2018). "Findings from this study indicate that binding of JUN (resulting from activation of JNK pathway) to the AP-1 binding site in the Sestrin2 promoter region is critical for the induction of Sestrin2 and consequent autophagy activation in cancer cells." (PMID 28690762, 2017). "In many cancers, protein levels of c-Jun are highly upregulated even in the absence of JUN amplifications or elevated transcription of the JUN gene." (PMID 27089238, 2016). "Furthermore, the expression of AML1-ETO leads to increased amounts of the phosphorylated JUN and ATZ genes, suggesting an increased activity of the MAPK pathway, which is crucial to the cancer process in many other cancer types." (PMID 27649156, 2016). "Importantly, MSH6, PTGS2, HDAC1, JUN, SLC2A1, and MMP1 were enriched in the pathway in cancer, of which MSH6 and MMP1 were candidate genes." (PMID 27034707, 2016).